INS (insulin)
Diseases named in the same sentence as INS in open-access papers (continued):
Sharing a sentence is not in itself a finding about the gene and the disease.
Obesity (continued). "During diet-induced obesity, infection with the rodent filarial nematode Litomosoides sigmodontis and treatment with filarial antigens improved glucose and insulin tolerance and increased the immune cell populations associated with a lean, insulin-sensitive phenotype." (PMID 40962954, 2025). "Patients with pre-existing obesity may have experienced more substantial metabolic improvements, including significant weight loss and improved insulin sensitivity, which are key drivers of glucose normalization and potentially result in higher remission rates." (PMID 40843316, 2025). "Additionally, modulating bile acid metabolism and the ECS through microbiome-based interventions could improve insulin sensitivity and reduce obesity risk." (PMID 40183584, 2025). "To explore the mechanistic relationship between insulin, aromatase and obesity-linked accelerated growth, we aim to investigate whether the binding of insulin to its receptor, while promoting linear bone growth, leads to advanced bone age through upregulation of aromatase expression." (PMID 41329658, 2025). "In parallel, obesity markedly increases the risk for developing CVDs, such as atherosclerosis, myocardial infarction, and heart failure, primarily through its adverse effects on systemic inflammation, impaired insulin sensitivity (insulin resistance, IR), and abnormal lipid metabolism." (PMID 41020888, 2025). "Additionally, while transitioning from obesity to non-obesity might reduce inflammation and improve insulin sensitivity, the metabolic damage caused by years of obesity may persist, leading to sustained kidney damage." (PMID 39894937, 2025). "A population-based study found that equivalent insulin sensitivity in obese Swedes corresponded to lower BMI and waist-circumference values among Iraqi men and women, indicating that standard European obesity cutoffs may underestimate metabolic risk in Middle Eastern groups." (PMID 41473668, 2025). "Moreover, obesity‐related inflammation disrupts insulin signaling, further increasing cancer risk." (PMID 40387523, 2025). "These actions, along with the decreased insulin requirements, can subsequently lead to weight loss and further enhancement in peripheral insulin sensitivity, an effect which is becoming increasingly important in light of the ever-growing prevalence of obesity among patients with T1DM." (PMID 40573112, 2025). "In a separate study of 72 patients with T1DM and overweight or obesity, liraglutide (1.2 mg and 1.8 mg) over 12 weeks resulted in modest reductions in glucose levels, HbA1c, and significant weight loss (5 ± 1 kg), along with small reductions in total insulin dose (-10-12 IU)." (PMID 40707821, 2025). "Thus, decreased irisin could be associated with decreased oxidative metabolism and insulin sensitivity in muscle during obesity, whereas increased irisin could be interpreted as a counterregulatory mechanism to overcome insulin resistance." (PMID 40171198, 2025). "Patients with obesity usually present accumulation of free fatty acids (FFAs) in liver, adipocytes, skeletal muscle, and pancreas, which causes lipotoxicity in pancreatic β-cells and inhibition of insulin signaling in the liver and muscles, along with the eventual occurrence of IR." (PMID 40568560, 2025). "Moreover, obesity in children is associated with chronic low-grade inflammation, insulin resistance, and impaired neurotrophic factor signaling, which may attenuate the normal BDNF response usually induced by exercise." (PMID 40724649, 2025). "Similarly, regular exercise, including both aerobic and resistance training, enhances insulin sensitivity and aids in weight management, which is particularly critical given the rising prevalence of obesity—a major risk factor for T2DM—among younger populations." (PMID 40658669, 2025).
Obesity (continued). "In individuals with obesity, the dynamic equilibrium of lipid metabolism is disrupted, leading to excessive serum free fatty acids (FFAs), increased leptin, and decreased adiponectin levels, all of which can deteriorate insulin sensitivity and subsequently increase the risk of T2D." (PMID 41322468, 2025). "This glucose intolerance was associated with impaired insulin sensitivity at 22 to 24 weeks of age, increased fasting glucose after a 4-hour fast, and a mild, but statistically significant increase in body weight, suggesting LL:AA mice are more prone to obesity than KI mice over time." (PMID 41004571, 2025). "Physical activity ensures better modulation of insulin plasma levels, improves tissue sensitivity to insulin, reduces levels of sex hormones involved in cell growth, optimizes immune system activity, and acts on energy metabolism, reducing the risk of overweight and obesity." (PMID 40364115, 2025). "Hence, brain response to insulin can adapt to short-term changes in diet before weight gain and may facilitate the development of obesity and associated diseases." (PMID 39984682, 2025). "However, preliminary findings suggest that EVs may serve as promising biomarkers of weight-loss-associated changes in insulin sensitivity, inflammation, endothelial health, and renal function in pediatric cohorts with obesity." (PMID 41150813, 2025). "Thus, our aim was to assess if fasting plasma insulin levels at 18-20gw in pregnant women with obesity from the TOP study are associated with abdominal fat deposition (i.e., abdominal/total fat mass ratio (FMr)) in newborns, independent of other maternal risk factors, including prePregBMI and GWG." (PMID 40646607, 2025). "Therefore, Rho GTPases and Rac1 could serve as critical mediators linking the metabolic dysfunction caused by obesity and systemic insulin resistance with the increased metastatic potential of TNBC​." (PMID 40629272, 2025). "Despite its limitations by low palatability and unpleasant odor, animal as well as human studies have shown that butyrate supplementation improves insulin sensitivity, reduces diastolic blood pressure, and increases energy consumption, which may aid in managing obesity, a key risk factor for T2DM." (PMID 40305160, 2025). "A more recent cohort of 973 non‐Hispanic White youth with obesity (age range 3–17.9 years) showed that the development of prediabetes is negatively associated with MCRI measured by the ratio of the incremental areas under the curve (AUC) of C‐peptide to AUC of insulin during a 2‐h OGTT." (PMID 40470991, 2025). "Furthermore, the interaction between BPA and estrogen receptors can interfere with leptin and adiponectin signals, by regulating energy balance and insulin sensitivity, these hormones contribute to metabolic dysfunction and elevate susceptibility to weight gain and obesity." (PMID 41226680, 2025). "Restoration of insulin sensitivity not only improves glycemic control but may also reduce the risk of chronic complications associated with persistent hyperinsulinemia, including cardiovascular disease, obesity, and metabolic syndrome." (PMID 40895680, 2025). "For endocrinologists, accurate prediction of obesity severity (e.g., BMI classification, visceral adiposity grading) is pivotal for early risk stratification of hormone-dependent comorbidities and for designing personalized interventions (e.g., lifestyle guidance, insulin sensitizers)." (PMID 41438294, 2025). "This combination of effects, enhanced insulin signaling, normalization of leptin activity, and a macrophage shift toward the M2 phenotype, suggests that anthocyanidins hold considerable therapeutic potential for mitigating chronic inflammation associated with obesity and insulin resistance." (PMID 41374016, 2025).
Obesity (continued). "It has been well‐documented that individuals with obesity and T2D exhibit a shift in muscle fibre composition, characterised by a reduction in oxidative Type I fibres and an increase in glycolytic fibres, which is closely linked to insulin resistance and mitochondrial dysfunction." (PMID 40256914, 2025). "Furthermore, inflammation may impair the development of insulin-sensitive tissues and adipocytes, contributing to a pro-inflammatory phenotype in offspring, with increased susceptibility to obesity, metabolic syndrome, and cardiovascular disorders." (PMID 41373994, 2025). "Existing epidemiological studies have shown that obesity‐related comorbidities, including altered adipokine secretion, chronic low‐grade inflammation, and abnormal insulin resistance, may represent potential mechanisms underlying the association between obesity and thyroid cancer." (PMID 40620232, 2025). "Therapeutic strategies targeting upstream obesity-related inflammation, through weight loss, anti-inflammatory agents, or insulin-sensitizing drugs, may offer dual benefits by attenuating both amyloid and tau progression, thus slowing or preventing AD trajectory." (PMID 41155642, 2025). "Consistent with a less pronounced obesity-associated microbial signature, wild-type mice receiving fecal microbiota of Acod1-/- littermates gained less weight, showed lower fat depots and liver weights as well as increased insulin sensitivity, compared with wild type donors." (PMID 38302438, 2024). "In vivo, IL-17 deficiency enhanced glucose tolerance and insulin sensitivity in young mice, but simultaneously promoted adipocyte differentiation, leading to the increased accumulation of adipose tissue mass, the onset of obesity and the metabolic syndrome development." (PMID 39011515, 2024). "Notably, various factors such as impaired insulin sensitivity, AGEs, obesity, and vitamin D deficiency may contribute to this association." (PMID 38962732, 2024). "Additionally, BPA’s interaction with estrogen receptors can interfere with leptin and adiponectin signaling, two hormones involved in energy balance and insulin sensitivity, further promoting metabolic dysfunction and increasing susceptibility to weight gain and obesity." (PMID 39519574, 2024). "Obesity has also been associated with the altered follicular fluid, the critical environment for oocyte development and granulosa cell steroidogenesis, with elevated concentrations of leptin, insulin, triglycerides, inflammation markers (e.g., lactate and C-reactive protein), and oxidative stress." (PMID 38455649, 2024). "Furthermore, liquid carbohydrates have a high glycemic index which may lower insulin sensitivity and raise postprandial blood glucose while raising the risk of obesity and overweight." (PMID 38658854, 2024). "In addition to age, sex and obesity indices, we observed direct associations of glucose, insulin, liver enzymes, CRP, and blood pressure with EAT thickness suggesting that individuals with cardiometabolic risk factors may potentially have higher EAT thickness." (PMID 38796541, 2024). "While the precise connection between obesity and erectile dysfunction (ED) remains unclear, the role of obesity in metabolic syndrome suggests that ED may be caused by underlying pathophysiological processes, including oxidative stress, inflammation, and insulin and leptin resistance." (PMID 39402470, 2024). "Since estrogen is known to inhibit adipose tissue inflammation leading to improved insulin-induced lipolysis, varying hormonal statuses between men and women might explain our observation that female mice are less susceptible than males to obesity." (PMID 39125804, 2024). "While obesity may upregulate apelin levels, this occurs only when the condition is associated with hyperinsulinemia; thus, what mainly produces this augmentation in apelin expression appears to be increased insulin." (PMID 39457235, 2024).
Obesity (continued). "In addition, higher circulating levels of insulin could impact cancer risk by regulating levels of sex hormone synthesis and chronic inflammation which in turn increase the risk of obesity-related cancer." (PMID 39317703, 2024). "Because the fetal endocrine pancreas already acquires an insulin response to fetal glycemia at 14–20 GW, fetal abdominal overgrowth risk appears early in pregnancy for women developing gestational glucose intolerance, especially for women with obesity and/or advanced maternal age." (PMID 38833438, 2024). "It was recently reported that sedentary behavior may independently decrease insulin sensitivity in children and adolescents at risk of obesity, and increased childhood body mass index (BMI) has been associated with mid-adulthood cardiovascular morbidities and premature mortality." (PMID 38173399, 2024). "Dietary MUFA have been associated with reduced risk factors for metabolic syndrome and cardiovascular diseases and may foster a healthy blood lipid profile, lower blood pressure, enhance insulin sensitivity, control blood glucose levels, and decrease the risk of obesity." (PMID 38281331, 2024). "Obesity may contribute to proximal GC development through several mechanisms, including obesity-associated gastro-esophageal reflux, insulin resistance, dysregulation of the levels of leptin, adiponectin, and ghrelin, and elevated levels of insulin-like growth factor (IGF)." (PMID 38339127, 2024). "Furthermore, other variants of SCD1 have been linked to alterations in a number of parameters that are closely related to lipid metabolism, including body mass index, risk of obesity and cardiovascular diseases, insulin sensitivity, inflammation, and serum cholesterol levels." (PMID 39408225, 2024). "Therefore, low HDL-cholesterol in patients living with obesity and with higher fat mass could simply be one of the consequences of the decrease in the insulin sensitivity of skeletal muscles caused by muscle fat infiltration." (PMID 38674801, 2024). "Additionally, insomnia may lead to metabolic disorders, affecting glucose metabolism and insulin sensitivity, thereby increasing the risk of obesity." (PMID 39511656, 2024). "Notably, ventromedial hypothalamus damage has been implicated in hyperphagia as well as obesity due to a direct effect on appetite control centers or due to the vagal tone disinhibition at the pancreatic beta‐cell level, resulting to insulin hypersecretion and obesity." (PMID 38599791, 2024). "Furthermore, reduced autophagy in the liver was observed in both diet-induced obesity and genetic obesity models, which could be explained by obesity-associated hyperinsulinaemia (insulin inhibits autophagy)." (PMID 39683397, 2024). "Furthermore, in white VAT and SAT, sulpiride decreased adipocyte expansion due to hypertrophy, and in the VAT prevented the expression loss of Prlr and insulin sensitivity markers Insr and Glut4, and decreased Hif1α (hypoxia marker) expression in obesity conditions." (PMID 38635745, 2024). "As already reported by several studies, HFD causes hepatic steatosis, obesity-related dysbiosis as well as cardiotoxicity, and an increase in hemodynamic (blood pressure and HR), zoometric (weight), and metabolic variables (glucose, insulin, leptin, and ghrelin)." (PMID 39530003, 2024). "Thus, the comprehensive characterization of typical obesity-related pathogenic events (i.e., abnormal insulin homeostasis, dyslipidemia, inflammation), combined with the application of high throughput multi-elemental approaches, enabled us to decipher the molecular imprint of parental obesity." (PMID 38238301, 2024). "Interestingly, obesity, a key precursor to IR, is linked to adipose tissue dysfunction, chronic inflammation, and the imbalanced secretion of adipokines such as leptin and adiponectin, which diminish insulin sensitivity." (PMID 38791447, 2024).
Obesity (continued). "The ablation of olfactory sensory neurons in lean mice elicits resistance to obesity and increased sympathetic tonus leading to thermogenesis, but if this loss occurs after obesity development, the reduced olfactory activity increases fat mass and insulin resistance." (PMID 39876968, 2024). "Furthermore, the conversion of MHO children to MUO is determined by the loss of insulin sensitivity, thus corroborating the hypothesis that MetS begins with obesity but requires IR to develop." (PMID 38133765, 2024). "Moreover, the obesity–cancer association may also be linked to the endogenous hormone metabolism dysfunctions also including insulin, bio-available sex steroids, IGF-1, and IGFBPs." (PMID 38785834, 2024). "The finding in children with overweight and obesity over a 13-year follow-up is consistent with a previous report in children with overweight and obesity where objectively measured ST was associated with increased insulin secretion over a 7-year follow-up period." (PMID 38441224, 2024). "Moreover, high insulin concentration in seminal fluid caused by obesity reduced male performance." (PMID 37324835, 2023). "Finally, we also know that SMS patients with RAI1 variants may have a higher propensity to obesity, but our results indicate a risk of developing higher insulin concentrations in mutated SMS patients than in those with a deletion of the 17p11.2 region." (PMID 37761412, 2023). "Therefore, therapies that target pathological ECM remodelling or fibrosis could become an attractive strategy for improving insulin action and its associated cardiometabolic complications of obesity." (PMID 37383542, 2023). "Since D8CM-induced impairment of insulin secretion was mainly mediated by GR activation, our system may be a useful model to analyze pancreatic β-cell dysfunction associated with an increase in glucocorticoid production in obesity." (PMID 37863964, 2023). "Research suggests that insulin and C-peptide levels are interdependent, and elevated levels of these parameters may promote atherogenesis, potentially increasing the risk of cardiovascular disease in people with obesity." (PMID 37373485, 2023). "Additionally, reproductive failure in women with PCOS and obesity have been speculated to be the result of a pro-inflammatory environment causing disturbances in insulin signaling pathways within the endometrium." (PMID 37152686, 2023). "Therefore, at this stage, we could postulate that the activation of AMPK is a major mechanism underlying the anti-adipogenic, thermogenic, insulin sensitivity improvement, and anti-obesity effect of XH." (PMID 38231665, 2023). "Studies in recent years have shown that LF exerts a protective effect in the course of obesity and improves insulin sensitivity, making it an effective component of dietary supplements for people struggling with excessive body weight, including those with a predisposition to obesity." (PMID 37238040, 2023). "Furthermore, LF levels were positively and negatively associated with insulin sensitivity and inflammatory parameters, respectively, an important observation since systemic low-grade inflammation commonly characterized individuals with obesity." (PMID 36986124, 2023). "In this regard, a prospective study with women with obesity undergoing bariatric surgery showed a marked fat mass reduction (50%) associated with a decrease in abdominal subcutaneous adipocyte volume (but not number), which was significantly associated with improvements in insulin levels." (PMID 37513538, 2023). "Humans who are exposed to high carbohydrate diets will not only lead to weight gain and obesity, but exacerbate glucose/insulin homeostasis which could be an important underlying mechanism associated with the progression of cancer independent of obesity or perhaps in synergy." (PMID 37007087, 2023).